LEP (leptin)
Diseases named in the same sentence as LEP in open-access papers (continued):
Sharing a sentence is not in itself a finding about the gene and the disease.
metabolic syndrome (continued). "We also determined whether any age-related changes in serum ALT were explained by metabolic syndrome components, adiposity-related biomarkers including leptin, adiponectin, ghrelin and interleukin-6 (IL-6), or other markers of hepatic function (bilirubin, albumin, gamma glutamyl transferase [GGT])." (PMID 21170382, 2010). "A recent study has shown that rats with metabolic syndrome exhibit increased visceral fat accumulation, including EAT, along with an imbalance in adipokine secretion and a significant rise in leptin levels." (PMID 40943899, 2025). "This study examined seasonal changes in insulin, adiponectin, leptin, and HOMA-IR levels among healthy individuals and those with metabolic syndrome (MS) in Chiang Mai, Thailand." (PMID 40863890, 2025). "This study evaluated the seasonal variation in insulin, adiponectin, leptin, and HOMA-IR levels among healthy individuals and those with metabolic syndrome (MS) in relation to ambient PM2.5 exposure in Chiang Mai, Thailand." (PMID 40863890, 2025). "Our data revealed that ECG and EGCG prevented weight gain, dyslipidemia, elevated SBP, increased leptin levels, high blood sugar, and motor impairment induced by olanzapine." (PMID 40969408, 2025). "Elevated leptin levels in SCI patients correlate with central obesity, metabolic syndrome, and cardiovascular risks." (PMID 41180179, 2025). "Furthermore, patients with metabolic syndrome present with a lower amount of EVs with medium size, which was related to fasting insulin levels accompanied by consequences of insulin sensitivity, while studies show leptin to mediate the release of EVs from breast cancer cells." (PMID 39203770, 2024). "An association between adipokines and GGT was also determined, with observed significance among leptin, adiponectin, and GGT (p < 0.001), suggesting a complex interplay among these biomarkers in the context of metabolic syndrome." (PMID 39771030, 2024). "In this line, other metabolic analytes such as leptin have been proposed as predictive markers for PCOS and metabolic syndrome separately." (PMID 39519371, 2024). "Significant increases in leptin, triglycerides, insulin, intra-abdominal fat, adipocyte area and HSL activity are found in a metabolic syndrome model of male Wistar rats." (PMID 38396865, 2024). "Pro-inflammatory cytokines like leptin, IL-6 and TNF-α are noted to be formed in adipose tissues during pathogenesis of metabolic syndrome, and the anti-inflammatory cytokine, adiponectin has the power to counteract their harmful sequels." (PMID 36826001, 2023). "Leptin (LEP) and omentin (OMEN) are proteins whose concentrations change with the development of the metabolic syndrome (MetS)." (PMID 37109160, 2023). "Direct effects for maternal metabolic syndrome were also shown for child mediators of HDL (B = − 0.086, 95% CI = − 0.117, − 0.052) and leptin (B = − 0.054, 95% CI = − 0.089, − 0.032) in all child development domains." (PMID 37013575, 2023). "LGZG, combined with dietary restriction and regular exercise, decreased the levels of TG, TC, LDL-c, and FFA in rat of metabolic syndrome, possibly due to the inhibition of the serum and liver levels of TNF-α, leptin, and PKB." (PMID 35586687, 2022). "Obese rats exhibited significant hyperglycemia and dyslipidemia (manifested by elevated plasma TC and LDL-C with increased AI), in addition to the elevated leptin level, as a result of increased adipose tissue mass." (PMID 35486321, 2022). "Patients with intestinal metaplasia and metabolic syndrome (I M - Me t S g r o u p) have elevated levels of VEGF, while leptin levels were associated predominantly with MetS and not with IM." (PMID 35712481, 2022). "Subjects with features of metabolic syndrome had higher levels of C-peptide, GIP, insulin, leptin, PAI-1, and lower levels of ghrelin, whereas overweight and obese individuals had increased levels of GIP, leptin, glucagon, and decreased levels of ghrelin." (PMID 35409072, 2022).
metabolic syndrome (continued). "Furthermore, a recent review of prospective cohort studies and short-term trials suggests that regular consumption of SSBs was associated with hyperuricemia and gout, which could further increase the risks for T2DM, CVD, and MetSyn, in addition to dyslipidemia, inflammation, and decreased leptin." (PMID 35380611, 2022). "The intrauterine exposure to hyperglycemia and placental methylation of leptin and adiponectin might lead to the development of leptin and insulin resistance and alter appetite circuits leading to postnatal hyperphagia, decreased satiety, and subsequent development of metabolic syndrome." (PMID 35706903, 2022). "Adiponectin, leptin, resistin, TNF-α and IL-6 are considered as possible serum markers of metabolic syndrome and their expression levels are majorly regulated by SREP-1c and PPAR-γ." (PMID 33917607, 2021). "The relationship between the serum leptin levels and the concentration of ACTH and cortisol has been found in patients affected by metabolic syndrome." (PMID 34359179, 2021). "The common key molecules that link metabolic syndrome and psoriasis are TNF, IL-17, CRP, leptin, and adiponectin." (PMID 34207504, 2021). "TG, glucose (GLU), high-density lipoprotein cholesterol (HDL-C), low-density lipoprotein cholesterol (LDL-C), and hormone (insulin, leptin, and adiponectin) levels were analyzed to assess the effects of PLA2 on metabolic syndrome." (PMID 33947969, 2021). "Among the genes with the strongest relationship with metabolic syndrome, CNR1—cannabinoid receptor 1 gene, LEP—leptin promoter gene, FTO—alpha-ketoglutarate-dependent dioxygenase gene, MC4R—melanocortin 4 receptor gene and VDR—vitamin D receptor stand out." (PMID 32272684, 2020). "Data from those uncontrolled studies is limited, yet, they have shown that leptin treatment decreases DNL improving hepatic steatosis and dyslipidemia." (PMID 33316927, 2020). "We also investigated relationships between omentin, leptin, sex steroids, SHBG, age, and metabolic syndrome (MS)." (PMID 32326011, 2020). "We also confirmed the presence of metabolic syndrome in HSB-fed mice by their high levels of blood glucose, altered glucose tolerance test, high serum levels of LDL cholesterol, triglycerides, and leptin." (PMID 31923234, 2020). "Collectively, our studies support that lipid-lowering actions are critical for glucose-lowering effects of leptin, and demonstrate that LEPRs in RIP-Cre25Mgn neurons mediate anti-dyslipidemia actions of leptin in an insulin-independent manner." (PMID 33071988, 2020). "In conclusion prepubertal males born with IUGR increased weight, insulin and leptin and decreased adiponectin, as compared to males born AGA, emerge as early metabolic syndrome characteristics." (PMID 30356143, 2018). "Significantly higher concentrations of leptin, chemerin, IL-6, and HOMA-IR and decreased adiponectin concentrations were observed in patients with the metabolic syndrome." (PMID 30627158, 2018). "In our study, we found that such variables such as BMI, waist circumference, WHR, TGs, HDL, leptin, adiponectin, chemerin, and IL-6 are related to HOMA-I, which in turn is related to metabolic syndrome." (PMID 30627158, 2018). "The plasma markers of this phenotype included: hyperglycemia, dyslipidemia and elevated plasma levels of ALT, leptin, TNFα and TLR2 and TLR4 activators." (PMID 26761430, 2016). "We have demonstrated that selected inflammatory and anti-inflammatory markers (CRP, adiponectin, leptin, resistin, and Lp-PLA2) are involved in both pathogenesis of metabolic syndrome and pathogenesis of psoriasis." (PMID 28097156, 2016). "Metabolic syndrome is widely considered as a low-grade inflammatory state including inflammatory cytokine (TNF-α) and the chemokines (leptin and adiponectin)." (PMID 26652604, 2015).
metabolic syndrome (continued). "Metabolic syndrome has been associated with TNBC in several studies, and is hypothesized to increase risk of TNBC through the association with leptin and adiponectin levels that disrupt cell signaling pathways involved in cell cycle regulation, angiogenesis and cell proliferation." (PMID 26405628, 2015). "In order to explore the possible mechanism of L-arabinose on metabolic syndrome, six target genes related to metabolism including TNF-α, leptin, IL-6, ACCα, CPT-1α, and CPT-1α were measured by real-time PCR in liver and adipose tissues." (PMID 26652604, 2015). "Additionally, we compared A-FABP with adipokines related to metabolic syndrome (MetS) such as leptin and adiponectin. premenopausal and 90 early postmenopausal middle-aged Caucasian women were subject to examinations." (PMID 24971341, 2014). "Ln SDNN was significantly lower in the NAFLD group after adjustment for age, sex, hypertension, dyslipidemia, metabolic syndrome, body mass index, smoking, estimated glomerular filtration rate, HOMA-IR, and leptin (P<0.05)." (PMID 23626730, 2013). "Aging is accompanied by an increase in serum leptin levels, proinflammatory cytokines, such as TNF-α, and prevalence of metabolic syndrome." (PMID 24455217, 2013). "Serum insulin, glucose, diastolic blood pressure, TG, leptin and CRP were significantly higher in metabolic syndrome group compared to obese and control groups." (PMID 22691465, 2012). "It has also been noted that the leptin levels correlate with body fat content and leptin levels decrease with testosterone replacement in T2DM and metabolic syndrome." (PMID 22505891, 2012). "In conclusion, this study suggests that leptin and CRP are strong predictors of not only cardiovascular disease but also metabolic syndrome in Taiwanese men and women." (PMID 22533665, 2012). "In particular, we showed an high prevalence (29.8%) of metabolic syndrome in PHPT patients, correlated with significant alterations of some fat adipokines, such as leptin and adiponectin." (PMID 22719761, 2012). "Odds ratio (95%CI) of metabolic syndrome according to sex-specific quartile of HMW-adiponectin, leptin and sOB-R." (PMID 21347230, 2011). "In both obese and non-obese individuals from European and US populations, leptin levels correlated positively with the metabolic syndrome." (PMID 40362681, 2025). "Although leptin was numerically higher in those with dyslipidemia, the lack of statistical significance warrants cautious interpretation." (PMID 40807227, 2025). "The serum leptin levels of patients with hypothyroidism were considerablyhigher (P=0.0001**) when compared to metabolic syndrome patients without hypothyroidism and controls." (PMID 40255297, 2025). "Although leptin tended to be higher in those with dyslipidemia, the difference was not statistically significant (p = 0.140)." (PMID 40807227, 2025). "In this regard, an alteration of Raw, marked by an increase in pro-inflammatory parameters, such as leptin, IL-1 beta, IL-8, and TNF-alpha, and a decrease in anti-inflammatory parameters, such as adiponectin and IL-10, has been seen in older adults with metabolic syndrome." (PMID 40095561, 2025). "All parameters of the metabolic syndrome were ameliorated by treating mice with leptin, but not with a high-fat diet, proving the point that the adipose tissue degeneration, due to the Nf-ya KO, was causative, not an epiphenomenon, of the unbalance." (PMID 39327506, 2025). "The comparison of thyroid profile and serum leptin levels among patients with metabolic syndrome who did not have hypothyroidism isof interest." (PMID 40255297, 2025).
metabolic syndrome (continued). "Although the serum leptin levels were elevated, our participants did not have metabolic syndrome, with average values being above normal but lower than those typically found in obese individuals." (PMID 39768291, 2024). "Previous studies have reported that the methylation frequency of leptin (LEP) and adiponectin (ADIPOQ) promoters may contribute to the development of metabolic syndrome." (PMID 38068941, 2023). "As a strong point of our study, we highlight the results that are in line with the literature, reinforcing the importance of considering the adiponectin/leptin ratio in obese patients with and without metabolic syndrome." (PMID 37571250, 2023). "This metabolic syndrome, however, did not increase further in severity after mycobacterial infection in the leptin mutant." (PMID 35933481, 2022). "We can conclude that in both species, the metabolic syndrome of the leptin mutant was not aggravated when the mutant was infected by mycobacteria." (PMID 35933481, 2022). "In both species, this metabolic syndrome was not aggravated further when the leptin mutant was infected by mycobacteria." (PMID 35933481, 2022). "In both species, this metabolic syndrome is not aggravated further when the leptin mutant are infected by mycobacteria." (PMID 35933481, 2022). "Many genes such as APOB, LPL, APOA1, LEP, CD36, IL-6, and APOE may play an important role in dyslipidemia." (PMID 36061816, 2022). "Previous research revealed that plasma leptin was positively correlated with CRP levels in psychiatric patients, and they could be significant predictors of metabolic syndrome." (PMID 36090349, 2022). "Thus, dyslipidemia with increased levels of total cholesterol and LDL-C has been observed in patients with defects in leptin function." (PMID 36579566, 2022). "It seems that leptin levels are affected by the existence of metabolic syndrome and not by the presence of intestinal metaplasia." (PMID 35712481, 2022). "In men with a BMI of 20 to < 25, participants with leptin > 97.5th group had significantly higher levels of HOMA-IR, LDL-C, UA, a higher proportion of central obesity (WC > 90 cm), metabolic syndrome, and lower levels of HDL-C than participants with leptin of 2.5th to ≤ 97.5th group." (PMID 35941672, 2022). "Dong and his group reported the enhanced leptin levels and decreased adiponectin levels in the serum and synovial fluid in OA with metabolic syndrome, as compared to OA without metabolic syndrome." (PMID 34638520, 2021). "Leptin particulates in cholesterol-regulating functions via proprotein convertase subtilisin/kexin type 9 pathway and down-regulates expression of LDL receptors in hepatocytes, leading to elevated plasma LDL-C levels and dyslipidemia." (PMID 33667284, 2021). "They found that leptin expression was higher in patients with knee OA and metabolic syndrome than in those with knee OA without metabolic syndrome." (PMID 34769215, 2021). "Clinical characteristics, including the presence/absence of metabolic syndrome, were recorded, and serum biomarkers, including adiponectin, leptin, and ghrelin, were assessed." (PMID 32849295, 2020). "Subjects in this group with metabolic syndrome showed lower serum adiponectin levels and higher serum leptin levels with respect to those without metabolic syndrome (P < 0.0001, P = 0.002, respectively)." (PMID 32849295, 2020). "In a study conducted in China, serum LEP levels were significantly higher in osteoarthritic patients with or without metabolic syndrome, suggesting the regulatory role of LEP in OA progression." (PMID 31878053, 2019). "There were significant differences (p < 0.05) in leptin, resistin, and visfatin as well as significant dyslipidemia among those with GDM compared to those without GDM." (PMID 31836012, 2019). "The median level of leptin in patients without metabolic syndrome was higher in the PCa group than in BPH group, but the difference was not statistically significant." (PMID 30186533, 2018).
metabolic syndrome (continued). "With and without adjustment for age and sex, metabolic syndrome was significantly associated with LAR, leptin and adiponectin." (PMID 28878827, 2017). "The prevalence of hypertension and dyslipidemia tended to be higher in diabetic than non-diabetic patients, while plasma leptin and sOb-R levels, and HRV parameters were not significantly different between the groups." (PMID 26338087, 2015). "Following treatment with L-arabinose, metabolic syndrome rats had an obvious reduction in body weight, systolic blood pressure, diastolic blood pressure, fasting blood glucose, triglycerides, total cholesterol, serum insulin, TNF-α, and leptin." (PMID 26652604, 2015). "In this paper we briefly describe the pathophysiologic role of four important adipokines (adiponectin, leptin, TNF-α, and IL-6) in the metabolic syndrome and review some of the clinical trials that monitored these adipokines as a clinical outcome before and after exercise." (PMID 24563869, 2014). "In this context, the present study aims to assess the way in which leptin levels are influenced by exercise stress testing in patients with or without myocardial ischaemia diagnosed with metabolic syndrome." (PMID 24616817, 2014). "In the present study, leptin values were not statistically significantly decreased after exercise in subjects with metabolic syndrome without ischemic heart disease (group 2)." (PMID 24616817, 2014). "The ratio of adiponectin/leptin in subjects with and without risks for metabolic syndrome that excluded waist girth was also examined using the Kruskal-Wallis rank test." (PMID 23533722, 2013). "Male participants with high concentrations of both leptin and CRP had a significantly greater waist circumference, metabolic syndrome incidence, FBG, and triglyceride levels and lower HDL-C than individuals with low concentrations of both leptin and CRP (P < 0.017)." (PMID 22533665, 2012). "The results obtained in the present study demonstrated that leptin decreased significantly with exercise in obese without metabolic syndrome group, and this is in agreement with another study." (PMID 22691465, 2012). "The predictive value of leptin levels for metabolic syndrome was not diminished upon adjusting for age, age and tobacco usage, and age, tobacco usage, and BMI in either sex." (PMID 21526991, 2011). "The correlation between metabolic syndrome and serum leptin quartiles was calculated independent of age, tobacco usage, and BMI in three models using binary logistic regression analysis." (PMID 21526991, 2011). "HIV-infected subjects with metabolic syndrome show disturbances in inflammation and adipokines: they have higher CRP (5.5 ± 7.0 vs. 3.9 ± 6.0 mg/l, P < 0.003) and leptin (9 ± 9 vs. 4 ± 6 ng/ml, P < 0.0001) and lower adiponectin (12 ± 8 vs. 15 ± 10 μg/ml, P < 0.0001) levels." (PMID 21232158, 2011). "Previous studies on the effect of soy on hormonal changes like leptin have not been conducted on patients with metabolic syndrome." (PMID 21526104, 2010). "Preliminary results of our group demonstrated that ob−/ob− mice with metabolic syndrome have increased expression of mtNOS and high mitochondrial NO yield and that mitochondrial inhibition is released by NOS inhibitors or by leptin infusion, both decreasing NO yield in the organelles." (PMID 18335029, 2008). "In these children, mean norepinephrine and leptin levels were increased compared with the children with metabolic syndrome and no SDB." (PMID 18762497, 2008). "Moreover, significant correlations between ghrelin and other hormones such as leptin and adiponectin, as well as with components of metabolic syndrome, have been observed in young adults but not in older individuals." (PMID 40843663, 2025).